S100A4 (S100 calcium binding protein A4)
Diseases named in the same sentence as S100A4 in open-access papers (continued):
Sharing a sentence is not in itself a finding about the gene and the disease.
tumor (continued). "There are also studies showing that the S100A4 gene promotes macrophage differentiation towards a tumor phenotype and suggesting that this gene is a possible target for tumor therapy." (PMID 40696413, 2025). "Our findings suggest that S100A4 accelerates tumor progression and promotes chemoresistance through the modulation of proliferation, susceptibility to apoptosis, and epithelial–mesenchymal transition/cancer stem cell properties." (PMID 39857966, 2025). "By integrating scRNA-seq data across various cancers, we propose that S100A4 in the TME leading to tumor resistance against neoadjuvant therapy." (PMID 40772225, 2025). "The presence of S100A4 and vimentin in WT-EVs suggests their combined role in shaping tumor plasticity and immune evasion." (PMID 40618999, 2025). "Several genes, including S100A4, ITGAV, and COL3A1, previously linked to tumor progression and poor prognosis, emerged in our study as robust prognostic indicators." (PMID 40943183, 2025). "In vitro experiments, S100A4 co-localized with α-SMA + fibroblasts and directly induced PD-L1 expression in tumor cells, linking CAFs secreted S100A4 to immunosuppressive PD-L1 upregulation." (PMID 40772225, 2025). "In parallel, the proliferation of human visceral SMCs was accelerated, accompanied by the increased expression of S100A4 only after stimulation with tumor factors from cachectic patients." (PMID 38339292, 2024). "For example, the family member S100A4, which is secreted by tumor and stromal cells, stimulates tumor angiogenesis, acting synergistically with VEGF." (PMID 38672647, 2024). "Additionally, S100A4 is an angiogenic factor that belongs to the calcium-binding protein family, and plays a critical role in the initiation and progression of cancer, whose upregulation is associated with a high incidence of tumor metastasis and poor prognosis." (PMID 38200591, 2024). "S100A4, a member of the S100 calcium-binding protein family, is expressed in various cell types, including fibroblasts, macrophages, and tumor cells." (PMID 39702305, 2024). "Some members of this family, such as S100A4, S100A8/A9, S100P, and S100B, mediate the interaction between tumor and stromal cells, and thus, have been implicated in tumor progression, angiogenesis, and metastasis." (PMID 38499391, 2024). "Extracellularly, in the tumor microenvironment, S100A4 interacts with RAGE in a paracrine manner, This interaction subsequently induces the release of pro-inflammatory factors IL-6, IL-8 and CXC-L10 which then convert monocytes into TAMs." (PMID 39830522, 2024). "Stromal cell-derived S100A4 modulates the tumor immune response, consequently to high expression in stromal cells of the tumor microenvironment (fibroblasts, T-cells, macrophages)." (PMID 39830522, 2024). "S100A4 promotes angiogenesis and a pro-tumor immune environment, contributing to metastasis through the release of paracrine factors and pro-inflammatory cytokines, whereas S100A8/9, via the RAGE receptor, activates NF-κB and supports tumor cell growth." (PMID 39456655, 2024). "Previous studies have shown that most of the S100A4+ cells were macrophages in colon and tumor tissues." (PMID 39664586, 2024). "In this context, S100A4 is another Ca2+-binding protein of significant importance in metastasizing tumors and is generally considered as biomarker for the tumor progression." (PMID 38165538, 2024). "Studies with animal models obtained through human tumor xenografts have suggested that the in vivo expression of the S100A4 member can favor the development and invasiveness of various types of tumors, including melanoma and pancreatic carcinoma." (PMID 38672647, 2024). "On the other hand, according to several studies, α-SMA+ or S100A4+ CAFs are also potentially anti-tumor." (PMID 38320998, 2024).
tumor (continued). "Elevated levels of S100A4 have been correlated with poor prognosis and increased tumor aggressiveness, making it a potential biomarker for disease progression and a target for therapeutic intervention." (PMID 39205741, 2024). "S100A4 can stimulate tumor cells to secrete numerous inflammatory cytokines, most notably IL-8 and CCL2, which then shape the TME toward a pro-tumor state and favor metastatic growth." (PMID 38611008, 2024). "S100A4 is significantly elevated in tumor cells 13, and it activates collagenase 3 transcriptional activity 14, thereby enhancing tumor invasion and metastasis." (PMID 38164183, 2024). "The S100 calcium‐binding protein family member S100A4 is upregulated in tumor‐promoting CAFs and frequently used as a marker to identify this population of CAFs." (PMID 38979935, 2024). "This process is mediated by the release of vascular endothelial growth factor A (VEGFA) from S100A4-positive/hypoxia-inducible factor-1α (HIF-1α)-positive tumor cells." (PMID 39273383, 2024). "S100A4 encodes a small calcium-binding protein that is commonly overexpressed in a range of different tumor types, and a growing body of evidence suggests that S100A4 has an essential role in the process of cancer metastasis." (PMID 39253583, 2024). "Further examination of S100a4 mRNA expression levels confirmed increased expression in YFP + tumor organoids compared to that in YFP + normal organoids, with a further significant increase in solid organoids." (PMID 36828915, 2023). "S100A4 is considered to be an important driver gene of tumor metastasis, which can not only promote the invasiveness of tumor cells, but can also regulate the tumor microenvironment." (PMID 37400459, 2023). "Immunofluorescence staining confirmed the presence of S100A6 and S100A4 proteins in the cancer subpopulation of primary human glioma, and their abundance was correlated with tumor grade." (PMID 37670392, 2023). "Chromatin-bound S100a4’s effect on metastatic outgrowth is quite different from intracellular S100a4, which normally plays a role in tumor motility." (PMID 36973439, 2023). "Therefore, S100A4+ tumor cells may be associated with the immune response and EMT." (PMID 37430270, 2023). "We demonstrate that chromatin-bound S100a4 in NEPs activates the RAGE receptor on neighboring tumor cells and enhances their metastatic outgrowth in the lung." (PMID 36973439, 2023). "Tomato-positive fibroblasts in the intra-tumor region were significantly reduced in the S100a4-Cre; Ext1f/f mice compared to the control mice." (PMID 36809261, 2023). "Tumor cells from the IgG and PD-1 groups were mainly clustered in the invasive and migrative branches (H3F3B+ and FOSB+ tumor cells), while cells from the SMI group were mainly clustered in the CSCs and EMT branches (NEAT1+ and S100A4+ tumor cells)." (PMID 37430270, 2023). "S100A4 is expressed in fibroblasts, keratinocytes, smooth muscle cells (SMCs), cardiomyocytes, tumor cells, and several other cell types." (PMID 37217870, 2023). "Gene expression analysis showed a 31.5-fold increase in S100A6 gene expression (and a 14.7-fold increase in S100A4 gene expression) in these cells compared with most tumor cells." (PMID 37670392, 2023). "The chromatin-bound RAGE ligand S100a4 activates RAGE receptors in neighboring surviving tumor cells, leading to Erk activation." (PMID 36973439, 2023). "We performed immunofluorescence staining to examine Ext1 and vimentin expression of Tomato-positive cells of Pan02 tumor tissue in S100a4-Cre; Ext1f/f; Lsl-tdTomato and control mice." (PMID 36809261, 2023). "Overexpression of S100A4 led to increased tumor cell invasion, metastasis, and angiogenesis and downregulation of S100A4 reduced VEGF and MMP9 expression." (PMID 37853467, 2023).
tumor (continued). "Our previous observations indicated that S100A4 can be expressed by both M1 and M2 macrophages in tumor tissues (unpublished data)." (PMID 36895491, 2023). "S100A4 stimulates basal like BCCs to secrete cytokines and converts monocytes into Tam like cells, thus having tumor supporting functions." (PMID 36560848, 2023). "S100A4 is considered to be an important driver gene of tumor metastasis and plays a significant role in the lung metastasis of tumors." (PMID 37400459, 2023). "In the peri-tumor region, we measured the thickness of the layer surrounding the αSMA (+) fibroblasts in the S100a4-Cre; Ext1f/f and control mice." (PMID 36809261, 2023). "Experimental downregulation of S100A4 expression in vitro and in vivo resulted in blockage of neutrophil-promoted tumor progression." (PMID 38275375, 2023). "By real-time RT-PCR analysis, the expression of Ifng, Tnf, and Il1β tended to be lower in the tumor of S100a4-Cre; Ext1f/f mice, and there was significant difference in Tnf expression." (PMID 36809261, 2023). "High expression of S100A4 can be found in patient tumor tissues, blood, and circulating tumor cells in many different cancer entities such as CRC, lung, breast, and prostate cancer." (PMID 36674695, 2023). "By real-time RT-PCR analysis, the expression of Mmp-7 was significantly higher in the tumor of S100a4-Cre; Ext1f/f mice." (PMID 36809261, 2023). "The results showed that the percentage of Tomato-positive fibroblasts in peri- and intra-tumor regions of S100a4-Cre; Ext1f/f mice was lower than that of control mice." (PMID 36809261, 2023). "Studies have shown that S100A4 protein can promote tumor invasion and metastasis, regulating a variety of cell functions." (PMID 37118659, 2023). "Although S100A4 cannot stimulate cell proliferation or induce tumour formation alone, it can stimulate the metastatic cascade in model fly and rodent systems by interaction with oncogenes such as rasVal12 and neu." (PMID 37509135, 2023). "S100A4+ tumor cells were highly populated in the SMI group, and the innate immune response and regulation of cell activation were enriched in this group." (PMID 37430270, 2023). "TFs in XIST+ and S100A4+ tumor cells were similar, particularly RUNX3, REL, STAT4, and E2F1, which regulate the EMT process." (PMID 37430270, 2023). "Recent studies have shown that targeting S100A4 has potential application value in tumor treatment, and the regulatory association between STC1 and S100A4 proposed in this study also provides theoretical support for targeting S100A4 for tumor treatment." (PMID 37400459, 2023). "In an intrasplenically xenografted mouse model, niclosamide was shown to inhibit the expression of S100A4 and thus used as an S100A4 inhibitor for tumor therapy." (PMID 37120617, 2023). "By real-time RT-PCR analysis, we observed that the expression of Cd80 and Cd86 tended to be lower in the tumor of S100a4-Cre; Ext1f/f mice and a significant difference in Cd80 expression was observed." (PMID 36809261, 2023). "Clusters 3 and 5, mainly enriched in the tumor and interface zones, were characterized by genes S100A4, AP1S2 and S100A6 that defined monocytes." (PMID 37644609, 2023). "We performed immunofluorescence staining to examine Ext1 and vimentin expression of Tomato-positive cells of MC38 tumor tissue in S100a4-Cre; Ext1f/f; Lsl-tdTomato and control mice." (PMID 36809261, 2023). "To examine how the HS-reduced stroma of S100a4-Cre; Ext1f/f mice affected tumor growth, we subcutaneously transplanted murine tumor cells into S100a4-Cre; Ext1f/f and control mice." (PMID 36809261, 2023). "Our data indicated that STC1 acted on the tumor microenvironment indirectly, whereas S100A4 plays a clear role in regulating the tumor microenvironment." (PMID 37400459, 2023).
tumor (continued). "The signaling cascade can be disrupted by mutations in β-catenin itself, as well as by mutations in the destruction complex molecules or frizzled receptor leading to overexpression of S100A4 and increased invasiveness of the tumor." (PMID 36674695, 2023). "In the realm of cancer, S100A4 is a transcriptional target of β-catenin and promotes tumor migration, invasion, and metastasis." (PMID 36835153, 2023). "Determination of S100A4 levels in tumor tissues or body fluids can predict the prognosis and metastasis of cancer patients in the early stages." (PMID 36235175, 2022). "S100A4 was selected for these further investigations since it was reported to promote the migration ability of endothelial cells, thereby enhancing tumor metastasis." (PMID 36361563, 2022). "Herein, we examined the role of the S100A4/NMIIA axis during tumor progression and vasculogenesis in GBM." (PMID 35392912, 2022). "S100a4−/− CD11b+ GAMs have increased phagocytic activity, which is critical to generate anti-tumor immunity." (PMID 35140215, 2022). "The stimulation of S100A4 attracts immune cells to the cancerous regions and promotes cytokine and growth factor secretion towards the tumor niche." (PMID 35965620, 2022). "Treatment of mice with these inhibitors resulted in reduced tumor growth, reduced invasion, and fewer colorectal cancer metastases at least in part due to lower levels of S100A4." (PMID 36235175, 2022). "In ILC, the expression of fibroblast-activation protein alpha and fibroblast-specific protein 1/S100A4 was higher in both the tumor and stromal cells than in NST." (PMID 35205688, 2022). "S100A4 expression was furthermore correlated with advanced tumor stages such as higher T, N and M stages." (PMID 35326507, 2022). "It is generally known that S100A4 exerts central roles in the pathophysiology of tumor metastasis, fibrotic diseases, and autoimmune disorders." (PMID 35165531, 2022). "Cd274 and Zbtb32 negatively regulate immunity, and S100a4, Rap1gap, Armc3, and Prkar2b promote tumor metastasis, This was consistent with the emergence of immunosuppression in the later stages of E. granulosus infection and with the hydatid cyst metastasis." (PMID 36569953, 2022). "In primary pancreatic ductal adenocarcinomas (PDAC), TM4SF1+ tumor cells had mutually exclusive spatial locations with S100A4+ tumor cells." (PMID 36313703, 2022). "Global S100A4 promoter demethylation induces an increase of tumor invasiveness, as demonstrated in both LSCC tissue samples and HEp-2 cell line treated with DNA methyltransferase inhibitor." (PMID 35406495, 2022). "Targeting of S100A4 by a specific antibody was further demonstrated to abolish endothelial cell migration, tumor growth and angiogenesis in mouse xenografts models of M21 melanoma and MIA PaCa-2 pancreatic cancers." (PMID 36232334, 2022). "Macrophage-derived S100A4 is the main source of extracellular S100A4, and S100A4 plays an important role in promoting tumor malignant development and mitochondrial metabolism." (PMID 35444235, 2022). "We found Protein S100-A4—another Ca2+-binding protein—to be under-expressed in all types of tumor tissue." (PMID 35681609, 2022). "Then, MRC2 and S100A4 gene expression analysis was undertaken using tumor and healthy paraffin-embedded prostatic tissue (n = 13)." (PMID 36613987, 2022). "The biological explanation for this is based on the roles played by S100A4, Ca-125, and mesothelin in promoting tumor invasion and metastasis." (PMID 35892879, 2022). "In vitro, we found that DOX treatment increased the release of S100A4 into the supernatants by tumour cells." (PMID 36207295, 2022). "After IHC staining, 74 (26.7%) tumor samples were scored with an IRS higher than 5 into the S100A4 high group and 203 (73.3%) as S100A4 low." (PMID 35326507, 2022).
tumor (continued). "We investigated the association between S100A4 and NMIIA expression, as well as the profiles of hypoxia-related molecules, and tumor vascularization status using clinical samples and cell lines of GBM." (PMID 35392912, 2022). "S100A4 has been reported to influence metastasis by promoting the movement and invasion of existing tumor cells, which leads to invasive metastasis." (PMID 36499426, 2022). "S100A4 is frequently overexpressed in a variety of human malignancies and drives metastasis by stimulating angiogenesis, promoting the migration of tumor cells, and by facilitating the adhesion of cells to the extracellular matrix." (PMID 35392912, 2022). "One of the intermediaries in the intercellular communication between heterogenous tumor cell lines is S100A4 protein." (PMID 35546077, 2022). "Whole-tumor evaluation with magnetic resonance imaging (MRI) and texture analysis have established a model that predicts S100A4 overexpression as an imaging biomarker of PDAC." (PMID 34527585, 2021). "S100A4 takes part in many aspects of tumor progression and invasiveness, such as the control of cell cycle, angiogenesis, cell adhesion and motility." (PMID 33918416, 2021). "Previous studies have shown that diverse stimuli, including growth factors, regulate S100A4 expression in cancer cells toward aggressive tumor features." (PMID 33946884, 2021). "Knockdown of S100A4 in tumor cells not only strongly impacts their survival but also reduces the stem cell-like phenotype of the tumors." (PMID 33789743, 2021). "S100A4 expression was positive in both invasive areas of the tumor transition zone (in situ to invasive) in the present study." (PMID 33761962, 2021). "As for the main tumor, in the majority of patients, S100A4 was expressed only in the areas of stroma and fibrosis but not in the tumor cell." (PMID 34078355, 2021). "S100A4 has a major role in tumor progress and metastatic expansion via transcription up-regulation by WNT signaling pathway." (PMID 33805347, 2021). "We found significantly reduced S100A4 mRNA expression in tumor tissues of mice, treated with S100A4-specific shRNA plasmids (median = 1.78), compared to treatment with control shRNA plasmids (median = 17.52; p = 0.021)." (PMID 35008201, 2021). "In contrast, as expected, the abatement of proliferating S100A4+ cells by GCV treatment remarkably inhibited the regrowth of TSA tumor grafts." (PMID 34145030, 2021). "In turn, we found a significant increase of DKK1 protein expression in the tumor tissues with reduced S100A4 expression (median = 35.94), compared to control treatment (median = 27.54, p = 0.024)." (PMID 35008201, 2021). "Patients with high S100A4 and low DKK1 expression levels in the primary tumor can be classified as high risk for OS." (PMID 35008201, 2021). "S100A4 reduces the expression of E-cadherin and β-catenin in cancer cells, while S100A4+ stromal cells enhance the stem cell-like phenotype of tumor cells." (PMID 36046433, 2021). "Within the pimonidazole-positive hypoxic tumor cell area, the grain-count was 1.6-fold higher in the human S100A4-positive area than in the human S100A4-negative area." (PMID 33994540, 2021). "S100A4 advances the formation of PMNs and builds a microenvironment suitable for the survival of malignant tumors, while an S100A4 siRNA (siS100A4) blocks the expression of S100A4 and inhibits tumor growth." (PMID 34142930, 2021). "IHC analyses of tumor samples demonstrated the expression of S100A4 in lymphocytes, macrophages, endothelium, and smooth muscle cells." (PMID 34209679, 2021). "This effected significant decrease in S100A4 at the protein level, accompanied by significant tumour nodule decrease after the 30-day study." (PMID 33807045, 2021).